CDKN1A (cyclin dependent kinase inhibitor 1A)
Diseases named in the same sentence as CDKN1A in open-access papers (continued):
Sharing a sentence is not in itself a finding about the gene and the disease.
cancer (continued). "Acquisition of chemotherapy-resistant cancer phenotype of RAMA 37-28 cells may also associate with the overexpression of widely described cell cycle regulator CDKN1A (P21Waf1/Cip1), which can induce cell cycle arrest, followed by reduction of cancer cell growth rate." (PMID 37239828, 2023). "Thus, these bioinformatic analyses support the hypothesis that loss of CDKN1A expression associated with unleashed CDK1 can be linked to CIN in human cancer." (PMID 33168930, 2021). "CDKN1A protein can protect cancer cells from cisplatin-induced apoptosis as the DNA synthesis of S phase is reduced by G1 arrest, suggesting that one major reason of causing cisplatin resistance is that low expression of miR-17 family can block the DNA synthesis through CDKN1A-induced G1 arrest." (PMID 26482648, 2015). "The alteration frequencies in cancer cell lines were as follows: CDKN1A (4%), DNAJB9 (6%), GABARAPL1 (5%), RAB1A (1.6%), and VAMP7 (0.6%), with amplification being the most common type of alteration." (PMID 41040512, 2025). "Despite ongoing research into the antitumor effects of NO, studies suggest that NO can induce cell-cycle arrest at the G1/S phase, promote apoptosis, decrease cancer stem-like cells, and upregulate tumor suppressor genes such as CDKN1A and RASSF1A." (PMID 40227440, 2025). "CDKN1A has been reported as a biomarker of radiation damage response in cancer patients undergoing total body irradiation." (PMID 40216867, 2025). "CDKN1A, a cyclin-dependent kinase inhibitor, plays a crucial role in cell cycle regulation and is often found to be dysregulated in various cancers." (PMID 40869429, 2025). "CDKN1A functions as an oncogene, promoting cancer cell proliferation by inhibiting apoptosis in NSCLC32." (PMID 38213729, 2024). "Current investigations into CDKN1A inhibitors for cancer therapies indicate promising possibilities for cardiovascular applications, which merit further investigation." (PMID 39512814, 2024). "Previous studies have reported that down-regulation of CDKN1A is not only related to the uncontrolled proliferation of cancer cells but also responsible for the resistance of some cell cycle-specific drugs such as CDK4/6 inhibitors and paclitaxel." (PMID 39268503, 2024). "Conversely, increased expression of LINC01164, VLDLR-AS1, and CDKN1A was observed in hypoxic cancer cells." (PMID 39236027, 2024). "Among them, the expressions of Cdkn1a, Hmga2, Thbs1 and Cdkn2a in MicroRNAs that promote cell differentiation in cancer pathways increased, indicating that the differentiation of SSCs is dominant." (PMID 38397131, 2024). "Cyclin-dependent kinase 1A (CDKN1A), and Polo-like kinase 3 (PLK3) are cell cycle inhibitors, but CDKN1A overexpression has also been associated with increased cell migration and cancer stem cell promotion." (PMID 38674080, 2024). "Select genes that were found to be associated with chemoresistance in other cancers included GDF15, THBS1, CDKN1A and CLU." (PMID 38673926, 2024). "It has been reported that EGR1 regulates CDKN1A expression, resulting in the senescence of cancer cells." (PMID 39512814, 2024).
cancer (continued). "Our results revealed gene signatures that are associated with disease-free and/or overall survival in several cancers and identified the cell cycle inhibitor CDKN1A/p21 as the major hub in PGCC and early progeny." (PMID 38447798, 2024). "Ribosomal protein S6 (p-S6) and p21 (also known as CDKN1A) are two proteins known to play central roles in other cancers." (PMID 38673889, 2024). "Cdkn1a has previously been reported as a marker of irradiation in cancer patients undergoing WBI and in murine models from our lab and others." (PMID 36604457, 2023). "The role of CDKN1A/p21 in various cancer types has been extensively studied using cell lines, primary cultures, and patient samples." (PMID 38139316, 2023). "In contrast, for CDKN1A, a well characterized inhibitor of cell cycle progression, the gene effect scores are positive for most cancer cell lines." (PMID 36681780, 2023). "The preferential SRSF3‐mediated processing of the paralogs miR‐17 and miR‐20a led to enhanced cell cycle progression and proliferation in both mouse pluripotent and human cancer cells through the regulation of the cell cycle inhibitor CDKN1A/p21." (PMID 37306233, 2023). "CDKN1A, also termed p21, is a pivotal regulator of the cell cycle and is engaged in multiple types of cancer, metabolic dysfunctional diseases, and inflammation." (PMID 37305039, 2023). "There is growing evidence suggesting the involvement of CDKN1A expression in various malignancies, such as tonsillar, gastric, lung, and brain cancers." (PMID 37730565, 2023). "By contrast, CDKN1A and CDKN2A encode p21Cip1 and p16Ink4a, respectively, which are potent cell-cycle inhibitors in MCL, whereas FHL1 has been revealed to induce G1 and G2/M cell-cycle arrest by activating CDKN1A in human cancers." (PMID 36675119, 2023). "Conversely, stabilisation of CDKN1A/p21 at both the mRNA and protein levels promotes cell cycle arrest in cancer cells." (PMID 38139316, 2023). "CDKN1A/p21 is also involved in the DNA damage response in adult stem cells, implying that it plays a role in the survival of cancer stem cells after chemotherapy and therefore resistance." (PMID 38139316, 2023). "Cancers carrying BRAF mutations have increased the expression of cell cycle inhibitors, including CDKN2A, CDKN1A, and CDKN1B." (PMID 38020918, 2023). "As CDKN1A (p21) is a hub gene in cancer regulation, the modification of CDKN1A m6A is worthy of study." (PMID 37182151, 2023). "In this comprehensive review, we provide an overview of the multifaceted functions of CDKN1A/p21, present clinical data pertaining to cancer patients, and delve into potential strategies for targeting CDKN1A/p21 as a therapeutic approach to cancer." (PMID 38139316, 2023). "Knockdown of CMTR1 inhibited cancer cell growth both in vitro and in vivo, with a concomitant reduction in the expression of cell cycle-related genes, such as CDKN1A, CDK6, and CCND1." (PMID 37024465, 2023). "Considering senescence, the contradictory role of CDKN1A/p21 in cancer progression is important, as its upregulation induces a senescence-like phenotype in diverse cell lines." (PMID 38139316, 2023).
cancer (continued). "The repression of CDKN1A/p21 in cancer cells decreases their angiogenic capacity in vitro by upregulating the angiogenic factor thioredoxin." (PMID 38139316, 2023). "The current study concluded that ALKBH5 exerted cancer-promoting effects in NSCLC by suppressing CDKN1A (p21) or TIMP3." (PMID 35318440, 2022). "In cancer cell lines, overexpressed CDKN1A has been found to enhance cell death responses following DNA-damage induced by cisplatin." (PMID 36548180, 2022). "Since mRNA expression of Cdkn1a and Cdkn2a, which are representative senescence marker genes, is regulated by UHRF1 in lymphocytes and cancer cells, the cellular phenotypes caused by UHRF1 depletion can resemble those of cellular senescence." (PMID 35472067, 2022). "It has been reported that most of the 8 ARGs (VIM, UFM1, TSC2, SRC, MEFV, CTTN, CFTR and CDKN1A) are related to cancer." (PMID 35121801, 2022). "Apigenin, a major compound identified in our MOL has been previously reported to have contributed to the inhibition of several different types of cancers via the overexpression of CDKN1A." (PMID 36197921, 2022). "Knowledge of the regulation and function of CDKN1A in cancer cells has opened up several areas of investigation and led to novel therapeutic strategies." (PMID 34516353, 2021). "In contrast, the repression of Cdkn1a, Cdkn2a, Adam10, Pten and muscle-specific genes in different cancer cell lines or myoblasts cells depends on recruitment of HDAC1, hence, deacetylation of lysine residues in N-terminal tails of histones." (PMID 33731112, 2021). "Kaempferol can reduce the level of the cMyc mRNA and increase the level of the CDKN1A mRNA in cancer cells." (PMID 33868436, 2021). "There was also a strong decrease in the CDKN1A copies in all cancer cells, which can suggest a possibility of participation in cell cycle arrest." (PMID 33807874, 2021). "Although CDKN1A expression is often dysregulated in a variety of cancers, its expression has been shown to be either increased or decreased depending on the cancer and cell type." (PMID 34837932, 2021). "The mechanism of action of CDKN1A in ferroptosis still needs to be explored in greater depths to assess its role in the development and treatment of cancer." (PMID 34007410, 2021). "Some studies have shown that it can promote cell senescence, and the expression of CDKN1A in cancer cells often changes." (PMID 34988109, 2021). "Many of these miRNAs are upregulated in cancers with altered expression of CDKN1A, suggesting a synergistic effect of miRNAs." (PMID 33800703, 2021). "Blood from these pediatric cancer patients also showed higher baseline levels of Cdkn1a expression compared to healthy controls, demonstrating the importance of addressing the effects of confounding factors on expression changes." (PMID 34364390, 2021). "Exosomal miR-98-5p can be transferred to cancer cells and induce resistance to cisplatin through direct expression inhibition of cyclin-dependent kinase inhibitor 1A (CDKN1A, p21)." (PMID 33920605, 2021). "APTR represses the CDKN1A/P21 promoter, which has been correlated with cell proliferation in several cancers." (PMID 33777725, 2021).
cancer (continued). "Data on the prognostic relevance of CDKN1A expression are controversial in the literature and seem to be dependent on cancer type." (PMID 32079343, 2020). "And studies have shown that SAHA generally fights against cancer by upregulating the p21 (CDKN1A) cancer suppressor gene, PTEN, p27 and decreasing levels of pro-growth genes CDK2, CDK4, cyclin D1 and cyclin E." (PMID 32682428, 2020). "MAPK signalling pathway (JUN, RAC1, MAPK8, MYC and FOS) and transcriptional misregulation in cancer (CDKN1A, MYC and FOXO1)." (PMID 32457348, 2020). "The expression of CDKN1A was equally upregulated in a dose-dependent manner in both cancer cell lines and increased threefold (RK33 *** p < 0.001; TE671 **** p < 0.0001) versus the control in the presence of 100μM IMP." (PMID 32353989, 2020). "Knockdown of HDAC7 led to G1/S arrest in different cancer cells through the upregulation of the cell cycle inhibitor CDKN1A (p21)." (PMID 31482051, 2019). "The current study intends to explore the function of cancer-associated fibroblast (CAF)-derived exosomal microRNA-98-5p (miR-98-5p) in cisplatin resistance in OC, and the participation of CDKN1A." (PMID 31889899, 2019). "The TGF-β cytostatic program in epithelial cells involves, among other molecular events, the induction of Cdkn1a and Cdkn2b but cancer cells utilize any opportunity to circumvent TGF-β ability to inhibit cell proliferation." (PMID 31036808, 2019). "Cyclin-dependent kinase inhibitor 1A (CDKN1A, p21), belonging to the Cip/Kip family, has been identified as a target of anti-cancer drugs." (PMID 31889899, 2019). "There was also a strong decline of CDKN1A copies in all cancer cells what suggests the possibility of participation in cell cycle arrest." (PMID 31801304, 2019). "In the previous study, we showed that TRA2β4 accelerated cancer cell growth by downregulating p21 expression through an inhibition of Sp1 binding to the CDKN1A promoter." (PMID 29928487, 2018). "In untreated HCT116 cancer cells, significant reductions in the expressions of CDKN1A were found, as compared to the normal colon cells (HCEC; data not shown)." (PMID 30214687, 2018). "Correlation analysis of the dataset GSE76297 (92 pairs of cancer and 91 normal tissue samples) from the Molecular Signature Database suggested that CDKN1A was substantially negatively correlated with EZH2 and SNHG1." (PMID 29970899, 2018). "Histone deacetylase 4 (HDAC4) and Cyclin-dependent kinase inhibitor 1A (CDKN1A) are two critical proteins in cancer, and both are directly targeted and regulated by miR-22." (PMID 28045918, 2017). "Knockdown of CDKN1A rescues the cell viability of cancer cells transfected with siRNA targeting MAGE-A12." (PMID 28978129, 2017). "Some of them have been reported to be cancer-associated genes such as CDC25A, CDKN1A, MMP1, MMP13 and SOX4." (PMID 27863388, 2016). "Next we measured CDKN1A expression under conditions of drug-induced stress imposed by treatment of cells with the cancer-inhibiting agent, piperlongumine (PL)." (PMID 25838973, 2015). "For example, it was reported that HIF-1α expression inversely correlates with Sp1 binding to the CDKN1A promoter region in cancer cells." (PMID 26703734, 2015). "RNA interference-mediated inhibition of HIF-1α expression induced by the iron-depriving agent desferrioxamine increases Sp1 binding to the CDKN1A promoter region in cancer cells." (PMID 26703734, 2015). "It is down-regulated in prostate cancer and re-expression of Esrrb in prostate cancer cells inhibited cancer cell proliferation through tumor suppressor Cdkn1a/p21 induction." (PMID 26597826, 2015).
cancer (continued). "Four further protein-truncating and missense CDKN1A mutations were found, and of the total of six CDKN1A-mutant cancers in our set, two (33%) showed LOH." (PMID 24777035, 2014). "In agreement with a tumor suppressive role of this gene, many human cancers exhibit low levels of p21 protein, and experimental ablation of CDKN1A promotes tumor formation in mice." (PMID 23457546, 2013). "TBX2 and its close relative, TBX3, negatively regulate cell cycle control genes and CDKNs, specifically CDKN2A, CDKN2B, and CDKN1A and are often upregulated in several cancers." (PMID 22829758, 2012). "Cdkn1a has previously been shown to be subject to epigenetic control in various types of cancer and is highly methylated in cirrhotic liver." (PMID 21779332, 2011). "This was the first Brazilian study to analyze the most frequent CDKN1A gene polymorphisms (codon 31 and 3’UTR site) and protein expression relating to the second most frequent category of pediatric cancer (CNS tumors), in comparison with a control population." (PMID 20169278, 2009). "Three of these SNPs (CDKN1A-S31R, OGG1-S326C, and XRCC3-T241M) have already found to be associated with altered cancer risk." (PMID 16111488, 2005). "Consistently, loss of 9p21.3/CDKN2A,CDKN1A were observed in virus-negative cancers (OR = 4.96, 95% CI = 3.65–6.73, q = 1.77e-25)." (PMID 40595559, 2025). "In non-cancer mouse cells, circFoxo3 binds to the cell cycle-associated proteins CDK2 (cyclin dependent kinase 2) and p21 (CDKN1A, cyclin dependent kinase inhibitor 1A), reducing the formation of cyclin E/CDK2 complexes, thereby blocking the G1 to S phase transition in the cell cycle." (PMID 39966624, 2025). "Notably, one of these clusters exhibited a significant expression of cancer‐promoting genes, encompassing Cdkn1a, Plaur, Ptgs2, Cox17, Lilrb4q, G0s2, Egr1, and Cxcl2." (PMID 39113226, 2024). "In addition, STAT3 has also been identified as a regulator of CDKN1A transcription in various cancer cells." (PMID 38553760, 2024). "In contrast, CDKN1A has positive co-dependency with PHLDA3, another factor involved in the intrinsic apoptotic pathway and RAP2B, which is implicated in proliferation and migration of cancer cells." (PMID 36681780, 2023). "High CDKN1A expression correlates with disease severity in many cancers." (PMID 36765862, 2023). "However, the highest concentration of PPE (100 μg/mL) led to a significant increase (p<0.05) in CDKN1A level in cancer cells OVCAR-3, as compared to control." (PMID 38027211, 2023). "Indeed, the anti-cancer properties of berberine have been shown to be partly due to the increased nuclear localisation and stability of CDKN1A/p21." (PMID 38139316, 2023). "Patient data analysis reveals that CDKN1A/p21 shows a notable preference for Luminal A type and HR (Hormone Receptor) subtypes following cancer patient stratification, which could hold significant implications for treatment options." (PMID 38139316, 2023). "However, elevated CDKN1A expression occurs in many cancers including HCC that correlates with poor prognosis, suggesting an oncogenic role of CDKN1A." (PMID 36765862, 2023). "Changes in the expression of numerous genes (CDKN1A, SMAD3, MLH1 and PIK3IP1) caused by mutations in ARID1A contribute to the development of cancer and have been linked to the PI3K/AKT pathway in cell translocation, which was highly likely to become a therapeutic target for OC." (PMID 37525498, 2023). "However, CDKN1A/p21 has also been documented to promote cancer progression by stabilising cyclin D1–CDK4 complexes and inhibiting apoptosis." (PMID 38139316, 2023).